IGFBP1 (insulin like growth factor binding protein 1)
Diseases named in the same sentence as IGFBP1 in open-access papers (continued):
Sharing a sentence is not in itself a finding about the gene and the disease.
glioma (8 papers, 2017 to 2025). A benign or malignant brain and spinal cord tumor that arises from glial cells (astrocytes, oligodendrocytes, ependymal cells). "Further, it was reported that IGFBP1 expression was upregulated by eightfold in experimentally induced RG7388 resistant glioma cells." (PMID 32414222, 2020). "Thus, IGFBP1 expressed by microglial cells in response to glioma-expressed MCSF was perhaps the main origin of tumor angiogenesis." (PMID 35419058, 2022). "Furthermore, microglia produce IGFBP1 in response to glioma-derived CSF1, and IGFBP1 has been shown to induce angiogenesis in glioma cells." (PMID 34503065, 2021). "The transient knockdown of IGFBP1 significantly restored the cellular sensitivity towards RG7388 indicated that IGFBP1 is one of the most promising candidates that can be targeted to overcome drug resistance in glioma." (PMID 32414222, 2020). "Enhanced gene expression of IGFBP1 and IGFBP2 has been demonstrated in meningiomas and gliomas." (PMID 28786923, 2017). "Likewise, Igfbp1 knock-down alleviates the hypoxia-induced growth retardation in zebrafish, whereas the IGFBP4 expression is induced by hypoxia in U87 glioma cells." (PMID 31354511, 2019).
Hypertension (8 papers, 2016 to 2024). The presence of chronic increased pressure in the systemic arterial system. "rs2854843 and rs13223993 variations were associated with lower IGFBP1 levels in the hypertension cases (all P <0.05)." (PMID 29100429, 2017). "Lower IGFBP1 levels are associated with hypertension and CVD risk factors." (PMID 29100429, 2017). "Lower serum IGFBP1 levels may predict an increased risk of hypertension." (PMID 29100429, 2017). "Our results showed that the serum IGFBP1 levels linearly increased with the variations in rs1065780 both in the controls and in the hypertension cases (Ptrend=0.001)." (PMID 29100429, 2017). "The median (interquartile range) of serum IGFBP1 in the hypertension cases [16.77 (6.97, 50.35) ng/ml] was significantly lower than that in the controls [32.37 (10.12, 73.72) ng/ml], P=0.011." (PMID 29100429, 2017). "Three single-nucleotide polymorphisms (SNPs) in IGFBP1 and four SNPs in IGFBP3 were selected for genotyping in 2,012 hypertension cases and 2,210 healthy controls and 4,128 subjects were followed up for a median of 5.01 years." (PMID 29100429, 2017). "Herein, we evaluated the association of seven SNPs of IGFBP1 and IGFBP3 with hypertension in a community-based case-control study of the Chinese Han population as well as with CCVD in a prospective follow-up study." (PMID 29100429, 2017). "The serum levels of IGFBP1 significantly varied among the genotypes of rs1065780, rs2854843 and rs13223993, both in the controls and in the hypertension cases (P<0.05)." (PMID 29100429, 2017). "Studies in the adult population showed that different IGFBP1 gene variants may have an effect on blood pressure, and the concentration of IGFBP1 in the serum of people with hypertension was lower compared to the healthy individuals." (PMID 34371941, 2021). "Highly phosphorylated circulating levels of IGFBP-1 are closely correlated with macrovascular disease and hypertension in T2DM, whereas lesser phosphorylated IGFBP-1 isoforms are associated with glycemic control, suggesting a dual role for IGFBP-1 in the regulation of IGF actions in T2DM." (PMID 30392760, 2019). "Moreover, the hypertension cases presented with lower serum IGFBP1 levels than the controls (P=0.011)." (PMID 29100429, 2017). "Additionally, decreased IGFBP1 levels were observed in hypertension cases." (PMID 29100429, 2017). "Therefore, IGFBP1 and IGFBP3 are of particular interest as candidate genes for hypertension." (PMID 29100429, 2017).
intrauterine growth restriction (8 papers, 2011 to 2025). "There is evidence for a pathophysiological role for IGFBP-1 in hypoxia-induced intrauterine growth restriction (IUGR) through inhibiting the growth-promoting activities of fetal IGFs." (PMID 21931746, 2011). "Additionally, intrauterine growth retardation is associated with a decrease in IGF-I and an increase in IGFBP-1 and IGFBP-2 levels in fetal blood." (PMID 32635165, 2020). "Studies have shown that IGFBP-1 upregulation is correlated with intrauterine growth restriction in fetuses subjected to long-term chronic hypoxia; IGFBP-1 is also involved in the suppression of cell growth and proliferation in the euryoxic fish Gillichthys mirabilis after exposure to hypoxia." (PMID 30298021, 2018). "Additionally, lncRNAs and protein-coding genes, including IGFBP1 and EGFR-AS1, play roles in trophoblast regulation and angiogenesis, impacting PE and intrauterine growth retardation (IUGR)." (PMID 38674114, 2024).
ovarian carcinoma (8 papers, 2010 to 2024). A malignant neoplasm originating from the surface ovarian epithelium. "In ovarian cancer, the expression of IGFBP-1 is significantly correlated with ovarian risk." (PMID 34692659, 2021). "Noteworthily, a small molecule, BTYNB, act as promising therapeutics against ovarian cancer by inhibiting cell proliferation of IGFBP1-positive ovarian cancer cells." (PMID 32414222, 2020). "BTYNB was found to restrain the binding of IGFBP1 to c-Myc mRNA and downregulate mRNA transcripts, including c-Myc, eEF2, and β-TrCP1 in ovarian cancer cells." (PMID 32414222, 2020). "Both proteins had high concentrations in the high OC pool but only IGFBP1 showed a concentration dependence with the ratio of ovarian cancer sera to control." (PMID 20559444, 2010). "Though elevated serum levels of IGFBP2 have been demonstrated in a number of cancers, including ovarian, this is the first evidence that IGFBP1 levels increase in serum or plasma of patients with ovarian cancer." (PMID 20559444, 2010). "Also, it selectively reduces the levels of other cancer related IGFBP1 mRNA targets, including CDC34, BTRC, and COL5A, similar to the effect by knockdown of IGFBP1 in ovarian cancer cells." (PMID 32414222, 2020). "An increase in IL-3 and IL-10 expressions, insulin-like growth factor binding proteins (IGFBP) IGFBP-1, IGFBP-2 and IGFBP-3 levels were detected in both ovarian cancer cell lines with leptin administration." (PMID 37155466, 2023). "Insulin-like growth factor binding proteins (IGFBP) IGFBP-1, IGFBP-2 and IGFBP-3 were increased by leptin treatment in both ovarian cancer cells." (PMID 37155466, 2023). "Unfortunately, data on the protein expression level of IGFBP1 in ovarian cancer are lacking." (PMID 37199034, 2023). "Therefore, IGFBP1, FBN1, SERPINA1 not only have complex interactions with WT1, but also may jointly regulate the migration and invasion of ovarian cancer cells." (PMID 34692659, 2021).
coronary heart disease (7 papers, 2013 to 2024). "IGF1 and IGFBP1 have been found to associate positively with all cause and ischemic heart disease mortality in the elderly Rancho Bernardo cohort." (PMID 24373343, 2013). "Individuals with a history of ischemic heart disease (n = 75, mean 50 y) have lower IGFBP-1, particularly lesser phosphorylated forms, compared to controls." (PMID 39595651, 2024). "In younger males surviving a first myocardial infarction (n = 92, <45 y), IGF-I and not IGFBP-1 was independently associated with coronary artery disease progression over a five-year period." (PMID 39595651, 2024). "The present findings suggest that IGFBP-1–HIF-1α could be targeted for treating ischemic heart disease." (PMID 34531382, 2021). "Irrespective of diabetes, high IGFBP-1 serum concentrations were correlated with and thus predictive for an increased risk of cardiovascular and coronary heart disease mortality in elderly men." (PMID 30061864, 2018). "Furthermore, in a prospective study, it was found that low baseline levels of IGF-I and IGFBP-1 increased the risk of fatal ischemic heart disease among both elderly men and women independent of prevalent ischemic heart disease and other cardiovascular risk factors." (PMID 32190801, 2020). "In patients presenting with unstable angina, those with critical coronary artery disease (n = 67, mean 62 y, 25% F) had higher IGFBP-1 than those with noncritical disease (n = 45, mean 60 y, 64% F)." (PMID 39595651, 2024). "In this study, higher easily dissociable IGF-I was associated with decreased presence of atherosclerotic plaques and coronary artery disease, while IGFBP-1 was not." (PMID 39595651, 2024). "In healthy older adults (n = 1185, 51–98 y, 47% F), lower fasting IGFBP-1 and lower total IGF-I were independently and jointly associated with ischemic heart disease mortality, but not all-cause mortality during a 9- to 13-year follow-up." (PMID 39595651, 2024).
glioblastoma (7 papers, 2019 to 2022). The most malignant astrocytic tumor (WHO grade IV). "It was found that glioblastoma-derived M-CSF induces microglial cells to release insulin-like growth factor-binding protein 1 (IGFBP1) to promote angiogenesis." (PMID 31370819, 2019). "Moreover, the production of CSF1 by glioblastoma induces the release of the insulin-like growth factor-binding protein 1 (IGFBP1) by microglia which Is essential to promote vascularization and angiogenesis." (PMID 35311140, 2022). "IGFBP1 is also involved in the activation of O-GlcNAcylation of FoxO1 in pancreatic β cells by promoting AKT inhibition in cancer cell response to DNA damage and it promotes angiogenesis in glioblastoma." (PMID 32526853, 2020).
Hepatic steatosis (7 papers, 2014 to 2025). Steatosis is a term used to denote lipid accumulation within hepatocytes. "Thus, the loss of Wtap in the liver promotes hepatic steatosis mainly by increasing both lipolysis in eWAT and FFAs uptake in the liver due to increased expression of Igfbp1 and Cd36." (PMID 35927268, 2022). "Hepatic deletion of Wtap induces the expression and secretion of IGFBP1, which enhances lipolysis in the eWAT and increases serum FFAs, leading to hepatic steatosis." (PMID 35927268, 2022). "However, treatment with exogenous IGFBP1 was recently shown to improve hepatic steatosis and liver TG content and reduce serum ALT and AST in MASLD mice." (PMID 38542455, 2024). "IGFBP-1 concentrations are low in hepatic steatosis both in adults and in children." (PMID 26237614, 2014).
Hyperglycemia (7 papers, 2019 to 2024). An increased concentration of glucose in the blood. "Hepatic IGFBP-1 mRNA levels and IGFBP-1 plasma concentrations in the ovine fetus are increased by maternal fasting and fetal hypoglycemia and reduced by maternal and fetal hyperglycemia." (PMID 37764824, 2023). "This is thought to be due to low IGF-1 levels caused by the upregulated expression of insulin-like growth factor-binding protein (IGFBP-1) secondary to low portal insulin; this is the most likely mechanism of disease in our patient given his severe degree of hyperglycemia." (PMID 38793013, 2024). "In individuals with insulin-deficient GDM, IGFBP1 amounts were low in the first trimester but amounts during the second semester were on par with those without GDM, suggesting that other pathophysiologic factors contribute to hyperglycemia in this GDM subtype." (PMID 38627562, 2024). "The results, obtained in this work, also confirmed by other researchers, with regard to decreased IGFBP-1 in babies born to mothers with GDM, can be explained by hyperglycemia and an increased insulin concentration in the fetus, which inhibits the production of IGFBP-1 in the liver." (PMID 33053704, 2020). "Mice with oxygen-induced retinopathy alone versus oxygen-induced retinopathy plus streptozotocin-induced hyperglycemia/hypoinsulinemia were assessed for glucose, insulin, IGF1, IGFBP1, and IGFBP3 in blood and liver." (PMID 33004691, 2020).
Impaired glucose tolerance (7 papers, 2012 to 2023). An abnormal resistance to glucose, i.e., a reduction in the ability to maintain glucose levels in the blood stream within normal limits following oral or intravenous administration of glucose. "For example, IGFBP-1 is known to be lower in patients with impaired glucose tolerance." (PMID 35159232, 2022). "In a population-based study of individuals of European or Pakistan origin, IGFBP-1 was independently associated with impaired 2-hour glucose tolerance and every 2.7 ng/mL increase in IGFBP-1 was associated with a 40% risk reduction for developing impaired glucose tolerance." (PMID 32190801, 2020). "Our finding of the relationship of IGFBP-1 with glucose metabolism is in accordance with previous studies in non-pregnant subjects, in whom lower serum IGFBP-1 concentrations have been analysed in impaired glucose tolerance." (PMID 32923723, 2020).
Miscarriage (7 papers, 2017 to 2025). A pregnancy that ends at a stage in which the fetus is incapable of surviving on its own, defined as the spontaneous loss of a fetus before the 22th week of pregnancy. "Some studies suggested that a disordered decidual response or excessive decidual IGFBP1 may be associated with miscarriage, impaired fetal growth or spontaneous preterm delivery." (PMID 37244968, 2023). "Our study found that SGK1 and its signaling pathway-related proteins (p-Nedd4-2, 14–3-3 protein, ENaC-α), estrogen and progesterone and their receptors (E2, P, ERβ, PR), and decidualization markers (PRL, PRLR, IGFBP-1) were expressed at lower levels in unexplained recurrent miscarriage tissue." (PMID 37280474, 2023). "The dNK cell from miscarriage cases also secrete higher level of TNF-α, which inhibits ESCs decidualization by decreasing the decidual markers prolactin (PRL) and insulin-like growth factor binding protein-1(IGFBP-1)." (PMID 34512661, 2021). "The study demonstrated that 17‐OHP and IGFBP‐1 were not a predictors of miscarriage outcome, whereas Inhibin A and Inhibin pro aC did show statistically significantly differences between successful and unsuccessful outcomes." (PMID 39119791, 2024).
Nephropathy (7 papers, 2012 to 2022). A nonspecific term referring to disease or damage of the kidneys. "The IGFBP-1 gene has been suspected to be protective for nephropathy, possibly through altered IGFBP-1 binding to IGF-1 with local effect in the kidney." (PMID 22400116, 2012). "In addition, researchers explored the role of IGFBP-1 in other kidney disease." (PMID 35002740, 2021). "Additionally, the association between the plasma levels of NGAL, IGFBP-1, IGFBP-3, and IGFBP-4 in patients with DN were compared to those in patients with T2D without kidney disease and control participants." (PMID 35148702, 2022).
osteoporosis (7 papers, 2018 to 2025). A condition of reduced bone mass, with decreased cortical thickness and a decrease in the number and size of the trabeculae of cancellous bone (but normal chemical composition), resulting in increased fracture incidence. "We conducted a 2-sample Mendelian randomization (MR) study to assess the causal relationship between IGFBP 1-7 and osteoporosis using publicly available genome-wide association study summary statistics." (PMID 41305735, 2025). "This study used GWAS summary statistics to analyze the causal relationship between IGFBP 1-7 and osteoporosis." (PMID 41305735, 2025). "Earlier research on the same cohort has already revealed associations between levels of IGFBP-1 and osteoporosis, fracture risk and all-cause mortality." (PMID 39592711, 2024). "In the future, IGFBP1 antagonists are expected to be tested for the potential to decrease bone loss and alleviate osteoporosis." (PMID 36967758, 2023). "Additionally, IGFBP-1 is linked to osteoporosis, cognitive function, muscle mass and all-cause mortality, suggesting its involvement in systemic age-related disorders." (PMID 40286436, 2025). "The dataset with the largest sample size of IGFBP1-7 from the GWAS summary statistics was used as the exposure data, while the dataset with the largest sample size of osteoporosis was used as the outcome data." (PMID 41305735, 2025). "A large body of literature have also reported that IGF-1 and several IGF-binding proteins (IGFBPs), like IGFBP-1, 3, 4, and 5, were positively correlated with bone mass and could serve as independent predictors for the occurrence of osteoporosis and fracture." (PMID 29747606, 2018). "In conclusion, interference with METTL14 inhibited osteogenic differentiation of BSMCs by m6A modification of SMAD1 in an IGFBP1 manner, suggesting that METTL14 might be a novel approach for improving osteoporosis." (PMID 36319624, 2022). "A search in PubMed found no relevant information about the levels of FGF21 and IGFBP1 in patients with osteoporosis, and future studies are needed to determine whether either or both of these proteins may be differentially expressed by patients with osteoporosis." (PMID 36967758, 2023).
polycystic ovary syndrome (7 papers, 2015 to 2025). A disorder that manifests as multiple cysts on the ovaries. "For instance, IGFBP-1 being down-regulated by insulin has an important role in the pathophysiology of polycystic ovary syndrome (PCOS) by increasing the free, biological active IGF-I and augmenting the androgen generation in the theca layer." (PMID 35118400, 2021). "Both in normal human ovaries and polycystic ovaries, granulosa cells can secrete insulin-like growth factor-binding protein-1 (IGFBP-1) in response to follicular stimulating hormone." (PMID 30775682, 2018). "In line with this, metformin causes a marked increase in IGFBP-1 in non-pregnant women with the polycystic ovary syndrome." (PMID 32652973, 2020).
Hypoglycemia (6 papers, 2010 to 2024). A decreased concentration of glucose in the blood. "Future experiments will show if these findings are translatable to FGR reveal if chronic hypoglycemia elicits IGFBP-1 hyperphosphorylation in vivo similar to the degree observed in the in vitro studies in this report." (PMID 38194365, 2024).
idiopathic pulmonary fibrosis (6 papers, 2016 to 2025). Idiopathic pulmonary fibrosis (IPF) is a nonneoplastic pulmonary disease that is characterized by the formation of scar tissue within the lungs in the absence of any known cause. "Some studies have observed elevated serum IGFBP-1 levels in idiopathic pulmonary fibrosis (IPF), along with a decrease in IGFBP-1 following anti-fibrotic treatment." (PMID 41226289, 2025). "Increased serum concentrations of IGFBP-1 and -2 were observed in patients with pulmonary fibrosis and negatively correlated with systemic sclerosis-associated pulmonary fibrosis." (PMID 36499287, 2022). "Serum IGFBP-1 and −2 are increased in idiopathic pulmonary fibrosis and IGFBP-2 may be reduced by anti-fibrosing therapy." (PMID 27215343, 2016). "However, other studies suggest that despite elevated IGFBP-1 levels, anti-fibrotic treatment does not cause a significant impact on IGFBP-1 expression in idiopathic pulmonary fibrosis (IPF)." (PMID 41226289, 2025). "We conclude that serum IGFBP-1 and IGFBP-2 are increased in patients with idiopathic pulmonary fibrosis in comparison to healthy subjects." (PMID 27215343, 2016).
steatosis (6 papers, 2017 to 2024). Increased lipid within the cytoplasm of cells. "Elevated CD36, IGFBP1 (insulin-like growth factor–binding protein 1), and chemokine (C–C motif) ligand 2 (CCL2) expression leads to steatosis and inflammation in the Wtap-HKO livers." (PMID 37777158, 2023). "The most upregulated genes associated with steatosis in the macaque alcohol liver disease model (PPARGC1A, IGFBP1, and FASN) were not altered by acute SIV infection." (PMID 38400071, 2024).